MTOR (mechanistic target of rapamycin kinase)
Diseases named in the same sentence as MTOR in open-access papers (continued):
Sharing a sentence is not in itself a finding about the gene and the disease.
tumor (continued). "Besides, Some reports find mTOR inhibitor achieves an increasing anti-tumor effect when combining with other forms of drugs, such as anti-osteoporotic drug, extra terminal domain protein inhibitor, conventional chemotherapy drugs." (PMID 27177330, 2016). "But single inhibition of the PI3K/Akt/mTOR pathway at the right location would be preferable to induce significant tumor cell damage, as inhibition of both pathways may otherwise cause additional clinical side effects." (PMID 27626684, 2016). "Finally, with regard to tumours with PI3K and Ras pathway mutations, mTORC1 activity is a determinant of sensitivity to PI3K/mTOR inhibitors." (PMID 27897178, 2016). "Similar to the alterations in allogeneic transplant models, The iNOS expression in the splenic CD11b+ Ly6Chigh M-MDSCs of alloskin-grafted or tumor-bearing Lyzs-mTOR KO recipients were significantly decreased than WT recipients as detected by flow cytometry (P < 0.001)." (PMID 26833095, 2016). "Initially, tumor microenvironment modifications can induce mTOR to increase the translation of hypoxia-inducible factor 1 (HIF-1)/hypoxia-inducible factor 2 (HIF-2), which drive the expression of genes for hypoxic stress response, including angiogenic growth factors such as VEGF, PDGF-β, and TGF-α." (PMID 28074082, 2016). "As far as the role of DEPTOR in ESCC progression, we found that ectopic expression of DEPTOR inhibited the activation of AKT/mTOR pathway, and suppressed proliferation, migration, and invasion as well as in vivo tumor growth of ESCC cells with relatively low DEPTOR expression." (PMID 26893358, 2016). "Notably, the inhibitors of mTOR can demonstrate anti-tumor effect in OS by inhibiting cell growth and proliferation, which raises great interesting in exploring available drug targeting mTOR to improve survival rate of OS." (PMID 27177330, 2016). "For example, loss of chromosome 9q34 removes tumor suppresser genes TSC1 (an mTOR pathway inhibitor), NOTCH1 (a development and stemness regulator), and GRIN1 (a calcium regulating tumor suppressor)." (PMID 27391266, 2016). "Our data show that ZNF703 may contribute to tumor development in NSCLC by activating the Akt/mTOR pathway." (PMID 27650486, 2016). "Moreover, the identification of the main mediators of the anti-tumor effects of mTOR inhibitors are of great importance regarding the development of diagnostic techniques to predict the response of individual patients to targeted therapy." (PMID 26506236, 2016). "For this reason, the overall activation of the PI3K/AKT/mTOR pathway has been proposed to identify tumor types that could be sensitive to mTOR inhibitors." (PMID 27374081, 2016). "However, tumor cell-intrinsic PD-L1 signals also regulate immune-independent tumor cell proliferation and mTOR signals, among other important effects." (PMID 28798885, 2016). "Twenty percent of ccRCC have mutations in MTOR, TSC1, PIK3CA, and PTEN and indicates that deregulated mTOR pathways may also be critical in this tumor subtype." (PMID 27530247, 2016). "Knockdown of mTOR leads to attenuated CRC tumor growth both in vitro and in vivo; thus, mTOR inhibitors could be promising anticancer therapeutic options in CRC treatment." (PMID 27144580, 2016). "The LW group recruited various metabolic pathways (such as ketone body metabolism) that have the potential to increase tumour cell activity (i.e., enhancing Ki-67 and mTOR expression), however, the nutritional supplementation did not appear to benefit tumour growth." (PMID 27716121, 2016). "Moreover, here we identified that AKT/mTOR signaling activation in the tumor microenvironments played the key roles of RCC tumorigenesis and progression." (PMID 27283897, 2016). "mTOR pathway activation may lead to accumulation of hypoxia inducible factor, which promotes the transcription of angiogenesis- and tumor progression-related genes." (PMID 27231847, 2016).
tumor (continued). "Different cell populations in normal stomach express Muc5ac and bind GSII lectin but these markers were co-localized in cells from rapamycin-treated mice, suggesting that some tumor cells activate an aberrant differentiation program when mTOR signaling is inhibited." (PMID 26859571, 2016). "So we hypothesized that PD-1/PD-L1 binding might directly activate the intracellular AKT/mTOR oncogenic signaling in tumor cells to promote DLBCL progression." (PMID 27147575, 2016). "Combined use of these treatment modalities with mTOR inhibitors that are more effective at targeting CSCs thereby renders more effective tumor destruction, better disease control and overcome the CSCs-mediated tumor resistance associated with the use of traditional agents." (PMID 27826244, 2016). "The mammalian target of rapamycin (mTOR) is a key regulator of translation that controls cell growth, proliferation, survival, and angiogenesis, and which is frequently dysregulated in tumor cells." (PMID 27031247, 2016). "Furthermore, Western blotting analysis of tumor lysates showed that eIF4B Ser422 phosphorylation was more significantly reduced by the combined inhibition of Pim and mTOR as compared to the single inhibitions." (PMID 26848623, 2016). "In addition, there was a negative correlation (r=−0.51; Spearman's rank correlation coefficient) for HIF-1α and phospho-mTOR S2448 expression in pT1M0 tumours." (PMID 27291893, 2016). "Based on genomic analysis of the original tumor, the patient was started on a regimen that incorporated the mTOR (mammalian target of rapamycin) inhibitor, temsirolimus, given in combination with the alkylating agent, temozolomide, and the topoisomerase inhibitor, irinotecan." (PMID 27799065, 2016). "Our observation therefore suggests that increasing the tumor pH via inhibition of CAIX might potentiate the efficacy of mTOR inhibitors." (PMID 27153561, 2016). "Since ATR-1 treatment results in the up-regulation of Bad, we hypothesized that PI3K-Akt-mTOR may be involved in the ATR-1 mediated anti-tumor effects." (PMID 26931119, 2016). "Importantly, EL4 tumor growth is significantly slower in Lyzs-mTOR KO mice than in WT recipients (P < 0.01)." (PMID 26833095, 2016). "Further, decreased ERRα expression on acute lapatinib treatment in vivo in the NIC tumours is concomitant with decreased mTOR signalling, while lapatinib-resistant tumours exhibit restoration of mTOR signalling along with the re-expression of high levels of ERRα." (PMID 27402251, 2016). "A further substance used in the present study is PI-103, a novel synthetic small molecule of the pyridofuropyrimidine class, which is a potent and selective inhibitor of class I PI3K, mTOR and DNA-PK with therapeutic activity against a range of human tumor xenografts." (PMID 27224913, 2016). "Both are tumor suppressor genes that negatively regulate mTOR." (PMID 27374081, 2016). "We previously reported that a combination of grape polyphenols (RQC at 5μM each) was more efficient than individual compounds at 5μM at inhibiting Akt and mTOR activities, cell proliferation, cell migration, cell cycle progression and tumor growth in the MDA-MB-231 human metastatic BC cell line." (PMID 27285995, 2016). "All of the PAM PI3K, mTOR, or PI3K/mTOR inhibitors listed in the previous section may be viable methods of suppressing tumor acidosis by lowering HIF-1α levels." (PMID 26962408, 2016). "Similarly, inhibition of the kinase mammalian target of rapamycin (mTOR) inhibits tumor cell growth by inducing apoptosis and also reduces PD-L1 expression by the tumor cell." (PMID 27887656, 2016). "Notably, the molecular biology of tumour growth and muscle responses to exercise share many common effectors (for example, mechanistic target of rapamycin [mTOR] signalling and pro-angiogenic genes)." (PMID 27303646, 2016). "Indeed, we found that KRT17 promoted tumor growth by stimulating the Akt/mTOR pathway and glucose uptake." (PMID 27512993, 2016).
tumor (continued). "It is possible that at early time points when tumors are small, the injected virus could reach most parts of the tumors, providing a boost to tumor growth through activating the AKT/mTOR pathway." (PMID 27849011, 2016). "As BD-138T contains both EGFR amplification and PTEN deletion, we originally predicted that one or more of the EGFR inhibitors or mTOR inhibitors might be effective agents against this tumor." (PMID 27438149, 2016). "Several oncogenes including MYC, hypoxia inducible factor 1 (HIF1), phosphoinositide-3-kinase (PI3K), protein kinase B (PBK or Akt) and the mechanistic target of rapamycin (mTOR), have been known to be involved in the regulation of tumor metabolic reprogramming." (PMID 28040803, 2016). "HIF-, UPR-, and mTOR-dependent responses to hypoxia serve to tumor cells to survive these stress conditions and seem to act in an integrated way, influencing common downstream pathways affecting gene expression, angiogenesis, metabolism, cell survival, tumorigenesis, and tumor growth." (PMID 27081084, 2016). "More recently, a large number of new agents have been approved for RCC, several of which attack tumor angiogenesis by inhibiting vascular endothelial growth factors (VEGF) and VEGF receptors (VEGFR), as well as tumor metabolism, inhibiting the mammalian target of rapamycin (mTOR)." (PMID 27891227, 2016). "Their efficacy as mTOR inhibitors, and therefore metabolism inhibitors, may be assessed with changes in tumor pHe." (PMID 26962408, 2016). "Upregulation of PKM2 induced by mTOR is critical for aerobic glycolysis and tumor growth." (PMID 26918353, 2016). "Interestingly, the functional coupling of SLC1A5 and SLC7A5 glutamine transporters suggests that enhanced glutamine metabolism in tumor cells can contribute to drive tumor growth through activation of mTOR." (PMID 28040803, 2016). "In this study, we noted that high p-mTOR expression was correlated with tumor progression." (PMID 27026382, 2016). "Also, inhibition of mTOR using T cell-specific aptamers delivering mTORC1 specific siRNA or by Temsirolimus resulted in an enhanced anti-tumor effector response and vaccine-derived immunity." (PMID 27007050, 2016). "Notably, both modifications contribute to the inactivation of tuberin’s tumor suppressor function and inhibitory effect on mTOR activity and signalling." (PMID 26745281, 2016). "PD-1/PD-L1 binding might activate the intracellular AKT/mTOR oncogenic signaling pathway in tumor cells to promote DLBCL aggressiveness." (PMID 27147575, 2016). "Hence, clinical trials with selective enrolment are needed to shed more light on the clinical benefits of combined HER2 and PI3K/AKT/mTOR targeted therapy in tumours with PI3K/AKT pathway hyperactivation, including IRS4+ tumours." (PMID 27876799, 2016). "This suggests that activation of mTORC1 occurs downstream of the PI3K–PDK1–AKT cascade in tumours harbouring IDH1 mutations, supporting the notion that 2HG-mediated inhibition of KDM4A affects the stability of DEPTOR leading to mTOR activation independently of the PI3K/AKT/TSC1-2 pathway." (PMID 27624942, 2016). "In these tumors, an increase AKT/mTOR signaling also resulted in higher tumor recurrence." (PMID 27826244, 2016). "Our recent study showed that LIF activates the AKT/mTOR signaling in tumor cells." (PMID 26716902, 2016). "The authors propose that mTOR is a molecular hub linking LMP2A and MTA1-associated tumor malignancy and might be an interesting target in NPC treatment." (PMID 27231932, 2016). "miR-199a can downregulate mTOR (mechanistic Target of Rapamycin), c-MET (protein encoded by the MET gene), and its downstream effector ERK2, thus inhibiting cell proliferation, motility, and the invasive capabilities of tumor cells." (PMID 27775664, 2016).
tumor (continued). "More recently, mammalian target of rapamycin (mTOR) inhibitors such as sirolimus have shown promising results in reducing rates of cellular proliferation of AMLs in patients with TSC, as these patients are often found to have upregulation of mTOR in tumor cell lines." (PMID 28070443, 2016). "Therefore, inhibition of mTOR activity disrupts the balance between pro- and anti-apoptotic proteins, enhancing tumor cell death." (PMID 26821053, 2016). "In addition, 4E-BP3 is induced in tumours treated with mTOR inhibitors and evokes anti-proliferative effects." (PMID 27319316, 2016). "Finally, combined IGF/mTOR/ER inhibition was most effective in limiting tumor growth and markedly altered transcriptional activity in ER-positive breast cancer tumors." (PMID 27765027, 2016). "Furthermore, a selective PI3K/mTOR inhibitor, gedatolisib, efficiently blocked proliferation, colony and tumor formation, and induced apoptosis in resistant cell lines." (PMID 26999641, 2016). "PI3K/AKT/mTOR signaling links several tumor cell metabolic processes, including glycolysis." (PMID 27888634, 2016). "Also, we found that TRIM44 is required to maintain the aggressive and malignant phenotypes of lung cancer cells, and that TRIM44 increases EMT and cell cycle progression in tumor cells by activating the mTOR pathway." (PMID 27058415, 2016). "PI3K/Akt/mTOR pathway could induce the development of tumor via various pathways; for instance, activation of mTOR could inhibit autophagy as a critical regulator in the initial period of autophagy." (PMID 26985248, 2016). "In conclusion, targeting mTOR decreased tumor growth in 7 out of 15 TNBC PDX tested." (PMID 27374081, 2016). "In addition to direct mTOR inhibition, hypoxic conditions in the tumor microenvironment are also capable of rapidly inducing autophagy via induction of the hypoxia-inducible factor-1 (HIF-1) leading to mTOR inhibition." (PMID 27247826, 2016). "Together, our results reveal a new mechanism that macrophages in the RCC tumor microenvironment could increase RCC metastasis via activation of the AKT/mTOR signals." (PMID 27283897, 2016). "Thus, constitutive activation or ablation of proteins in the PI3K-Akt-mTOR pathway can result in uncontrolled cellular proliferation and tumor growth." (PMID 27589846, 2016). "In addition, a dual PI3K/mTOR inhibitor shows an promising result in treating OS cell, and this anti-tumor activity can be enhanced by MEK/Erk inhibitors." (PMID 27177330, 2016). "Interestingly, although the CDK4/6 inhibitor palbociclib and mTOR inhibitor everolimus were efficacious as monotherapies, long-term delayed tumor growth was only observed when co-administered with fulvestrant." (PMID 27472462, 2016). "However, to the best of our knowledge, this is the first report that identified histology-independent mechanisms of sensitivity to mTOR inhibitor in multiple tumor types." (PMID 26859683, 2016). "Adjuvant mTOR inhibition may not only enhance treatment of the primary tumor, but re-sensitize emerging resistant, metastatic cell populations to treatment and limit lymph node and distant lung metastasis, improving long-term survival." (PMID 27015118, 2016). "In addition, we experimentally observed that –as predicted by this hypothetic mechanistic relationship– the loss of function of MLL2 in cell lines derived from tissues in which MLL2 drives tumorigenesis renders tumor cells more sensitive to mTOR inhibitors." (PMID 27095575, 2016). "The rapalogs everolimus and temsirolimus interfere with mTOR signaling in tumor cells." (PMID 27418963, 2016). "Indeed, IDO1 down-regulation can impair both mTOR activation and Treg-dependent tumor immune escape mechanism." (PMID 27174915, 2016). "Other studies support that Akt, a member of the PI3K/Akt/MTOR pathway, could also drive tumor resistance to BRAFV600E inhibitors and thus simultaneous inhibition of those two pathways (BRAF and PI3K) is needed." (PMID 26802026, 2016).
tumor (continued). "Consequently, when the expression of PTEN is decreased, either inhibiting PI3K or controlling the PI3K-Akt-mTOR pathway in other ways can supplement PTEN's tumor suppression." (PMID 27506936, 2016). "In addition to the stimulating effects of IL-6 and IGF-1, loss of function mutations of the tumour suppression gene PTEN in several MM cell lines, results in phosphorylation of the mTOR substrates." (PMID 26097872, 2015). "Our data highlights that a tumor may nevertheless be targeted indirectly through the normal EC mTOR signaling pathway which maintains sensitivity to mTORC2 inhibition." (PMID 26295809, 2015). "We demonstrated that treatment strategies containing metformin significantly reduced tumor growth and metastasis in nude mice, and that metformin caused an increase in AMPK and PTEN activity and suppression of mTOR/p70S6K/S6, as well as invasion/migration-associated genes, e.g., MMP7, DCN and FN1." (PMID 25909163, 2015). "Herein, we treated these allograft and xenograft mouse models with the mTOR inhibitor, sirolimus, and demonstrated that sirolimus could efficiently suppress FLCN-deficient tumor growth." (PMID 26418749, 2015). "Interestingly, both cells of the immune system and of tumour entities require this type of coordination and therefore are influenced by inhibition of mTOR." (PMID 25699174, 2015). "Moreover, it is widely demonstrated that mTOR inhibition has a significant antiproliferative effect on pNET cell lines as well as on other tumor cells." (PMID 25999915, 2015). "Thus, HER2/PI3K/mTOR inhibitors have greater anti-tumor activity when combined with inhibitors of autophagy." (PMID 26637440, 2015). "Additionally, tumor volume and weight are significantly inhibited through the suppression of Akt, mTOR, and Stat3, accompanied by a decrease in the expression of MMP-2 and MMP-9 in vivo." (PMID 26202311, 2015). "Both mTOR and p-mTOR staining was more pronounced in the tumor center than at the invasive front." (PMID 26652716, 2015). "A significantly high level of phosphorylated Akt may be detected in tumor-expanded MDSCs and increased Akt activity results in subsequent activation of NF-κB and mTOR, two players in controlling MDSC function." (PMID 26285119, 2015). "The emerging different roles of S6K1 and S6K2 suggest that specific targeting of either isoform may be valuable in different tumour subtypes, and in comparison to present day’s mTOR inhibitors, further promote individualised therapies." (PMID 26698305, 2015). "We next asked whether combined inhibition of PI3K and of mTOR could further enhance IL-12p70 secretion by DC-tumor fusion cells." (PMID 26605345, 2015). "Temporal inhibition of mTOR by rapamycin in our mouse model resulted in delayed tumor latency." (PMID 26575021, 2015). "Inhibition of p-Akt and p-mTOR, in vitro, decreased tumor cell VEGF-C and VEGF-D significantly." (PMID 25884175, 2015). "Crosstalk between HH and PI3K/AKT/mTOR signaling has been observed in different tumor entities." (PMID 25749378, 2015). "Akt-dependent mTOR activation reportedly increases tumor angiogenesis." (PMID 26468982, 2015). "Furthermore, NGDN knock-down in K562/A02 cells resulted in the activation of multiple tumor-related signaling pathways, especially the mammalian target of rapamycin (mTOR) pathway." (PMID 25887473, 2015). "Our study provide the first evidence indicating that a dynamic feature of reprogramming cellular bioenergetics is present in tumor cells, and a potential important factor that mediates such shifting in tumor bioenergetics from aerobic glycolysis to mitochondrial respiration is mTOR." (PMID 25807077, 2015). "To investigate whether cordycepin could regulate PI3K/AKT/mTOR pathways to induce apoptosis in MA-10 tumor Leydig cells, we first examined levels of AKT and mTOR by western blotting." (PMID 26303320, 2015). "mTOR is becoming a potential therapeutic target for tumor metastasis." (PMID 25996501, 2015).